AFP (alpha fetoprotein)
Diseases named in the same sentence as AFP in open-access papers (continued):
Sharing a sentence is not in itself a finding about the gene and the disease.
tumor (continued). "With regard to the role of tumor markers in the investigation of Sertoli–Leydig cell tumors, elevated serum levels of AFP can rarely be observed as a result of the presence of heterologous hepatocyte elements." (PMID 37508611, 2023). "Meanwhile, we revealed that significance was correlated with multiple clinical features including alpha-fetoprotein, histological grade, tumor stage as well as TCGA molecular subtypes in TCGA." (PMID 36843949, 2023). "The proportion of patients with poor tumor differentiation (13.3%) was highest in the TBS > 7.9/AFP ≥ 400 ng/mL group (p < 0.001)." (PMID 36831544, 2023). "Next, we determined the performance of the GALAD score in subgroups of Latin American HCC patients with different AFP levels, tumor stages, and etiologies." (PMID 37708457, 2023). "Histopathological images with hematoxylin and eosin staining showed tumor cells with pale cytoplasm and the immunostaining for alpha-fetoprotein, sal-like protein 4, and Glypican3 was positive." (PMID 38089923, 2023). "The parameters of tumor burden, liver function reserves and AFP are well-known predictors of survival in intermediate stage HCC patients undergoing TACE19,26,31–33." (PMID 38007597, 2023). "Our analysis indicated a remarkable correlation of high-risk score with gender (P=0.042), tumor grade (P<0.001), TNM staging (P=0.008), AFP (P<0.001), and cancer history (P=0.002)." (PMID 37301543, 2023). "Accordingly, instead of depending solely on tumor size and the number of nodules, the Milan criteria were expanded to include different tumor markers, such as AFP." (PMID 38001597, 2023). "AFP was one of the first protein tumor markers identified and is widely used for tumor screening, diagnosis, and prognosis." (PMID 37138865, 2023). "The hepatic fibrosis markers (HA) and tumor serum markers (AFP) were dramatically higher in the DEN model group than in the normal control group, showing a time-dependent increase (all P < 0.05)." (PMID 37280673, 2023). "Seven variables were included in the final model: BCLC stage, prior transarterial chemoembolization and immunotherapy history, tumor number, prognostic nutritional index, log (alpha-fetoprotein), and log (platelet-to-lymphocyte ratio)." (PMID 37105140, 2023). "In the present cohort, because the tumor number was greater than 3 (score 2), only the patients with AFP levels at or less than 100 ng/mL (score 0) and the largest tumor at or less than 3 cm (score 0) were included." (PMID 36967432, 2023). "Nowadays, the refined approach mostly combines morphological parameters (number and size of tumors) and alpha-fetoprotein (AFP) concentration, which is a well-known surrogate of tumor biology." (PMID 37568778, 2023). "Hanley-McNeil analysis showed that the scoring model was significantly better than the GLR, SII, tumor number and AFP in the development cohort (P=0.001, 0.001, <0.001, 0.038, respectively)." (PMID 37152021, 2023). "Using binary logistic regression, tumor multiplicity (p = 0.020), AFP level (p = 0.009), and BED dose (p = 0.001) were considered significant for the OR rate." (PMID 38001665, 2023). "The combination of these three variables (tumor location, AFP, and PCA) yielded 86.4% sensitivity and 81.9% specificity, with an AUC of 0.903." (PMID 37538113, 2023). "Consistently, METTL3 knockout inhibited NAFLD-HCC development, as shown by reduced AFP and MRI measurements and the reduced tumor number (p = 0.019) and size (p = 0.042) at sacrifice." (PMID 37586322, 2023). "According to Youden index analysis, the best cut-off values for age, maximum tumor diameter, tumor number, AFP level, GLR, and SII were 55.00, 5.15, 1, 55.50, 133.98, and 334.46 respectively." (PMID 37152021, 2023). "Our study considered tumor burden, pretreatment laboratory inflammatory indicator and AFP response after treatment as essential biomarkers for survival outcomes." (PMID 37958306, 2023).
tumor (continued). "Laboratory tests revealed elevated tumor markers, alpha-fetoprotein, and beta-human chorionic gonadotropin." (PMID 37575730, 2023). "The nomogram demonstrated that the M stage contributed the most to prognosis, followed by surgery, chemotherapy, tumor size, N stage, AFP level, and T stage." (PMID 36798659, 2023). "In cytologic evidence, HCC patient's AFP is significantly associated with malignant degree of HCC and tumor activity." (PMID 36254376, 2023). "IHC staining revealed the tumor cells from the liver metastases were immunoreactive for markers including AFP, GPC-3, and SALL4." (PMID 37781207, 2023). "After the completion of bridging CDCT, most (61.5%) required both tumor markers (AFP, BHCG, LDH) and radiological imaging to assess the response; 69.2% of those would have patients proceed to HDCT and ASCT regardless of the biochemical and radiology response." (PMID 37504318, 2023). "High serum AFP expression is correlated with more biologically aggressive properties and unfavorable tumor behaviors in HCCs." (PMID 37737166, 2023). "High AGR2 expression was significantly correlated with high AFP and ALT levels, a high predicted risk metastasis signature score, a large primary tumor size and more advanced pathological stages of HCC." (PMID 36899352, 2023). "Male gender, higher number (>1) of tumor, larger size (>3.5 cm), bilaterality of tumors, increasing AFP (>20 ng/mL), and treatment with LRT were predictors of radiological‐histopathological discordance." (PMID 37326440, 2023). "The score is assessed at time of LT and derives from the sum of the largest viable tumor diameter and the number of viable tumors on explant, microvascular invasion on explant and alpha-fetoprotein levels (AFP)." (PMID 38201435, 2023). "Chemo-immunotherapy including oxaliplatin plus S-1 and PD-1 inhibitor terelizumab was given to this patient for 2 months until the serum AFP level decreased from 748.5 to 12.9 ng/mL and the tumor shrank." (PMID 37065996, 2023). "The PROSASH and PROSASH-II model, which consisted of serum albumin, bilirubin, AFP, macrovascular invasion, extrahepatic spread, and largest tumor size, were built for survival prediction of patients with HCC treated with sorafenib." (PMID 36911686, 2023). "The post-treatment AFP level (normal or abnormal), number of tumor and the distribution of mRECIST were significantly different between the two groups (P=0.025, P=0.025 and P=0.001, respectively)." (PMID 37215117, 2023). "Currently the CSF level of tumor markers AFP and β-hCG has been a routine examination for differential diagnosis and prognosis prediction." (PMID 37476834, 2023). "Analyses of TCGA and clinical samples showed that the DHX37 expression level was positively correlated with the AFP expression level and inflammatory infiltration around the tumor." (PMID 37958405, 2023). "T stage, N stage, M stage, AFP, tumor size, surgery, and chemotherapy were independent prognostic risk factors that were all included in the nomogram to predict OS in HCC patients with EBRT." (PMID 36798659, 2023). "The diagnostic accuracy was better when the two miRNAs were combined compared with either one of them individually and significantly outperformed the tumor markers alpha fetoprotein (AFP) and cancer antigen (CA) 19-9." (PMID 36831603, 2023). "In the present study, multiple tumor biological characteristics (PIVKA-II, AFP, and tumor histopathologic grade) and a traditional tumor morphological parameter were combined to stratify the outcomes of HCC patients after LT." (PMID 37988413, 2023). "A total of 33 patients had vascular invasion, 59 patients had a maximal tumor diameter ≤ 5 cm, 99 patients had an increased serum AFP concentration, 137 patients were positive for hepatitis B virus surface antigen and 95 patients had grade I or II tumors." (PMID 38050235, 2023). "Nevertheless, it has been demonstrated that age, sex, AFP, PIVKA-II, tumor number, or ECOG PS have little association with outcome." (PMID 37689775, 2023).
tumor (continued). "Intra-hepatic TAMs were associated with high HBV-DNA, high tumor differentiation, small tumor size, abnormal AFP and more tumor number." (PMID 35347503, 2023). "The proportions of cirrhotic patients were lowest in the TBS > 7.9/AFP < 400 ng/mL group, which also contained higher proportions of patients with high tumor burden who required major resection." (PMID 36831544, 2023). "In contrast, in the low-AFP group, tumor burden of up-to-seven criteria, OUT, was a predictor of early PD." (PMID 37296889, 2023). "Our findings support the prognostic impacts of the baseline tumor size, AFP, and ascites as important factors to consider in trial design." (PMID 36902673, 2023). "The maximum intrahepatic tumor size, macrovascular invasion, serum α-fetoprotein (AFP) level, and prior ATB were identified as significant factors associated with PD according to mRECIST." (PMID 36749777, 2023). "The model accommodates the clinical variables of gender (biological sex) and age alongside 3 serological tumor markers: AFP isoform L3 (AFP-L3), AFP, and PIVKA-II." (PMID 37938100, 2023). "Since metastasis via CTC occurs independently of the AFP phenotype of the tumor, a combination of both markers seems particularly useful." (PMID 38012205, 2023). "In a cohort of 38 samples from 20 patients, QUENCH’s effectiveness in detecting CTNNB1 ctDNA was assessed and compared with ddPCR ctDNA and AFP levels, evaluating correlations with tumor burden and treatment response." (PMID 38201440, 2023). "In this study, we also found that RRM2 was upregulated in HCC with a higher clinicopathological grade, such as T stage, pathologic stage, tumor status, histologic grade, and AFP level." (PMID 37056349, 2023). "Tumor marker levels [alpha-fetoprotein (αFP) and human chorionic gonadotropin (βHCG)] and lactate dehydrogenase (LDH) were within the normal range." (PMID 38098099, 2023). "The univariate analysis indicated pathological differentiation, tumor size, AFP, TNM stage, NLR score, and ALBI grade were significant indicators of OS." (PMID 37208618, 2023). "A similar phenomenon was also observed in the combined effect survival analysis of serum AFP and tumor number." (PMID 37833735, 2023). "Among these parameters, AFP, Child–Pugh, tumor size, BCLC stage and serum miR-221 level were selected for multivariate analysis." (PMID 37685331, 2023). "The authors suggested that these changes in AFP values at HCC diagnosis were possibly related to the increasing trend in early-stage tumor detection and the shift from viral (i.e., hepatitis B virus (HBV) or hepatitis C virus (HCV)) to nonviral etiology." (PMID 36831565, 2023). "The clinical tumor marker alpha-feto-protein (AFP) was detectable at low protein levels in three out of four of the primary human liver cancer cell lines." (PMID 38201286, 2023). "The independent predictive factors for ER were the LI-RADS category, serum AFP level, tumor diameter, TBIL, start time, iso-time, and enhancement type." (PMID 37519810, 2023). "If a future expansion over the up-to-seven criteria is considered in Spain, a progressive increase in serum AFP and tumor progression on the waiting list despite locoregional ablative therapies should be kept as red flags to preclude LT." (PMID 38138897, 2023). "Alpha-fetoprotein, lactate dehydrogenase, aMAP score, diameter of main tumor, number of intrahepatic lesions, and treatment regimen were independent risk factors for prognosis." (PMID 37283795, 2023). "The median values of other tumor markers (Ferritin, A19-9, AFP, CEA, B2M) for the PanNEN patients with bone metastases and those in the non-bone metastatic group were also not significantly different (p > 0.05)." (PMID 37510802, 2023). "In this study, we developed a continuous flow immunoassay device based on a piezoelectric (PZ) quartz crystal biosensor fabricated with whole-electrode occupation for the quantitative molecular diagnosis of tumor markers such as alpha-fetoprotein (AFP)." (PMID 37887110, 2023).
tumor (continued). "Some patients had elevated serum AFP, indicating higher levels of differentiation in the hepatoid tumor area and a worse prognosis." (PMID 36816961, 2023). "The receiver operating characteristic analysis revealed that AFP > 31.8 ng/mL and a total tumor size >3.85 cm raise the likelihood of HCC recurrence post-LT." (PMID 37909200, 2023). "Among these factors, treatment type, Child–Pugh class, pretreatment AFP level, and tumor size were statistically significant in the multivariable analysis." (PMID 37370774, 2023). "The aim of this study was to assess the role of AFP changes after the first TACE in the prediction of complete tumor necrosis in patients with HCC." (PMID 37568778, 2023). "The technique selected for bridging therapy is dependent on patient condition, such as tumor size, number of nodules, and AFP concentration." (PMID 38001637, 2023). "Tumor markers revealed alpha-fetoprotein (AFP) was 24,760 ng/mL, carcinoembryonic antigen (CEA) was 1.9 ng/mL, and cancer antigen 19-9 (CA19-9) was 86 U/mL." (PMID 37791221, 2023). "Tumor markers play a leading role in monitoring, with changes in AFP levels reported to be useful markers for effectively monitoring of drug therapy and local treatment." (PMID 37296889, 2023). "This was consistent with previous reports that the reduction of AFP following NAC, together with tumor shrinkage rate, were significantly related to the risk of tumor recurrence." (PMID 37124543, 2023). "The dynamic changes in AFP expression with tumor evolution and the different compositions of AFP‐producing adenocarcinoma cells in each period can partly explain the clinical mismatch between serum AFP levels and immunohistochemical properties." (PMID 37017469, 2023). "On multivariate analysis, larger tumour size, raised AFP level and higher Child–Pugh class continued to be independently associated with PVT in HCC." (PMID 37533945, 2023). "In the present study, the LI-RADS category had a higher HR than the tumor diameter and serum AFP level, indicating that the LI-RADS category was an important independent predictive marker." (PMID 37519810, 2023). "The univariate analysis of survival demonstrated that HBV infection, Child–Pugh class, maximal tumor diameter, AFP, BCLC stage, treatment modality, ERBB2, and NRG4 were significant risk factors." (PMID 37174100, 2023). "The Hangzhou criteria can be further divided into two categories: Category A: tumor diameter ≤8 cm or tumor diameter >8 cm and AFP ≤100 μg/L; and Category B: tumor diameter >8 cm and AFP 100–400 μg/L." (PMID 38137734, 2023). "The favorable tumor marker decline was defined as tumor marker normalization within 9 weeks for AFP and 6 weeks for β-HCG, which correspond to three cycles and two cycles of chemotherapy treatment, respectively." (PMID 37046659, 2023). "While for patients with positive AFP before surgery (i.e., AFP response = 0), the reduction of tumor size needs to exceed 111.2% using the mRECIST measurement method to achieve a pCR." (PMID 37158833, 2023). "The impact of AFP on the creation of an immunosuppressive environment for the developing tumor was identified, giving rise to attempts at immunotherapy." (PMID 36768863, 2023). "NAFLD-HCC seems to be often diagnosed at more advanced stages than HCV-HCC, it usually occurs with a larger tumor size and infiltrative pattern, being frequently detected in non-cirrhotic livers and outside-specific surveillance, with lower AFP levels." (PMID 36831120, 2023). "There were significant differences in tumor staging, AFP, CA125, CA199, and ALP between the NOM and OM groups (p < 0.05)." (PMID 37795569, 2023). "Serum miR-122 correlated with the BCLC stage but did not correlate with other clinical parameters, including sex, age, biochemical parameters, AFP level, Child–Pugh classification and tumor size." (PMID 37685331, 2023).
tumor (continued). "We have also previously reported that AFP is a useful tumor marker for the initial efficacy evaluation of sorafenib, lenvatinib, and Atezo + Beva for HCC." (PMID 37190231, 2023). "Our present clinical experience indicates the importance of histological examination for determining AFP-positive anterior mediastinal tumor treatment." (PMID 37721573, 2023). "In the present study, we found that AGR2 is significantly correlated with OS, RFS, and various clinical parameters, including AFP, ALT, the predicted risk metastasis signature score, tumor size, and pathological stage." (PMID 36899352, 2023). "Patients with EpCAM-positive alpha-fetoprotein (AFP)-positive HCC are usually young but have advanced tumor-node-metastasis (TNM) stages." (PMID 36674932, 2023). "In our study, the AFP value and total tumor size had an impact on the recurrence of HCC, and the survival rates were comparable on LDLT and DDLT." (PMID 37909200, 2023). "This would explain our finding of significantly higher BCLC stage and Child-Pugh Score at presentation and a trend towards a larger median diameter of the largest tumour lesion and AFP during the pandemic." (PMID 37989352, 2023). "In the multivariate analysis, we observed that male patients who were under 65 years old with tumor sizes < 3 cm and a lower preoperative AFP level (<400 ng/mL) who were treated with combination therapy but were without ascites had a significantly better PFS." (PMID 36902673, 2023). "Surveillance programs rely on the dosage of serum alpha-fetoprotein and the execution of abdominal ultrasound to detect early-stage tumours." (PMID 37509293, 2023). "Tumor cells from patient #4001 were characterized by overexpression of AFP, GPC3, DUSP9, DLK1, GLUL, and AXIN2, a marker of Wnt/β-catenin pathway activation." (PMID 37932266, 2023). "The levels of serum tumor markers, lactate dehydrogenase, alpha fetoprotein, and human chorionic gonadotrophin were in a normal range." (PMID 37843278, 2023). "Results showed that the untreated controls had the highest level of ALT, AST, ALP and AFP indicating liver damage and high tumour burden." (PMID 36874031, 2023). "Our results found that patients in different groups divided by tumor parameters (including AFP level, tumor number and largest tumor size) have close Metabolites-Score, which indicated our model is applicable to all kinds of HCC patients." (PMID 36845695, 2023). "Next, characteristics that had a significant correlation (p<0.005) with FDG-avid lesions were entered as logistic regression, such as Ki-67 index, tumor differentiation, AFP and HePpar-1 status, conventional factors (age, sex), and MTV were used to correct." (PMID 37682282, 2023). "The combination of AFP, PCA, and tumor location had a good diagnostic performance in the discrimination of GHA from GA with 86.4% sensitivity, 81.9% specificity and an AUC of 0.903." (PMID 37538113, 2023). "Age, naïve or recurrence, sum of the size of the largest tumor nodule, the number of nodules, total bilirubin, albumin, AFP and DCP were significantly different." (PMID 38007597, 2023). "In HCC tumor tissues, AFP is found intracellularly and extracellularly via presentation by a major histocompatibility complex (MHC) class I molecule." (PMID 38173713, 2023). "The predictive performance of our CR model is similar to previous studies, but our model had a higher AUC value and higher specificity than Feng’s model, which included AFP, tumor necrosis, and hemorrhage, possibly due to the contribution of lab test results." (PMID 37197418, 2023). "Since AFP was identified as a tumor marker for HCC, it has been used for diagnosis, prognosis, and surveillance of HCC." (PMID 37700838, 2023). "In the case of the Metroticket 2.0 model, the inclusion criteria was further refined to consider both tumor size and number and actual AFP value." (PMID 38001597, 2023).